ZNF264 (zinc finger protein 264)
Description:
May be involved in transcriptional regulation.
Synonyms: KIAA0412
Tractability: PROTAC: UniProt records ubiquitination sites on it; ubiquitination databases record sites on it.
Gene: Protein-coding gene on chromosome 19 (57,191,500 to 57,222,846, forward strand). Ensembl gene ENSG00000083844.
Subcellular location: Nucleus
Subcellular location (Human Protein Atlas): Nucleoplasm
Pathways (Reactome):
Gene expression (Transcription): Generic Transcription Pathway; Regulation of endogenous retroelements by KRAB-ZFP proteins
Gene Ontology:
Molecular function: protein binding; DNA-binding transcription factor activity, RNA polymerase II-specific; RNA polymerase II cis-regulatory region sequence-specific DNA binding
Biological process: regulation of transcription by RNA polymerase II; regulation of DNA-templated transcription
Cellular component: nucleus
Genetic constraint (gnomAD): Loss-of-function variants: 12 observed, 10.43 expected, observed/expected ratio (o/e) 1.15, 90% interval 0.73 to 1.77. The upper end of that interval is the gene's LOEUF score, 1.77, which puts it in group 6 of 6, group 1 being the genes least tolerant of losing a copy. Missense variants: 747 observed, 789.76 expected, observed/expected ratio (o/e) 0.95, 90% interval 0.89 to 1. Synonymous variants: 309 observed, 290.06 expected, observed/expected ratio (o/e) 1.07, 90% interval 0.97 to 1.17.
Homologues: Orthologues: chimpanzee ZNF264 (99% identical), rabbit ZNF264 (84% identical), Drosophila melanogaster CG3281 (21% identical), Drosophila melanogaster CG2712 (20% identical), Drosophila melanogaster Phs (19% identical). Paralogues in human: ZNF805 (85% identical), ZNF599 (52% identical), ZNF550 (38% identical), ZNF133 (36% identical), ZNF266 (36% identical), ZFP90 (36% identical), ZNF582 (36% identical), ZFP37 (35% identical), ZNF25 (35% identical), ZNF404 (35% identical), ZNF875 (34% identical), ZNF425 (34% identical), and 50 more.
Diseases named in the same sentence as ZNF264 in open-access papers:
ZNF264 is named in the same sentence as 8 diseases in open-access papers, as found by Europe PMC text mining. Sharing a sentence is not in itself a finding about the gene and the disease. The quoted sentences say what the papers report.
mental retardation (1 paper, 2021). "ZF proteins like ZNF264 contribute to coordinated gene expression changes during brain aging and ZNF711 is reportedly associated with mental retardation and cognitive disability." (PMID 34494552, 2021).
Obesity (1 paper, 2022). Accumulation of substantial excess body fat. "As a result, we found GWAS signals relevant to obesity around rs2870099 as follows: rs34863160 (ZNF470), rs11670527 (DUXA, ZNF264), and rs16987303 (ZNF471) were associated with birth weight, BMI, and height, respectively." (PMID 36276968, 2022).
uterine corpus endometrial carcinoma (1 paper, 2021). A endometrial carcinoma (disease) that involves the body of uterus. "For example, an RNA‐editing site residing in ZNF264 indicates poor survival of uterine corpus endometrial carcinoma, with a hazard ratio of 2.13 and an adjusted p‐value of 4.07 × 10−7." (PMID 34319007, 2021).
cancer (4 papers, 2021 to 2025). A tumor composed of atypical neoplastic, often pleomorphic cells that invade other tissues. "ZFP2 and ZNF264 are zinc finger proteins regulating gene expression; their dysfunctions can cause developmental abnormalities and cancer." (PMID 40141456, 2025). "Other transcription factors are associated with cancer-related pathways, such as NPAT, ZNF264, HEYL and ETV4." (PMID 33525507, 2021). "The heatmap showed that the 15 CpG sites (located on B3GALNT1, C6orf97, FAM72A, FAM72B, LIFR, OSMR, ZNF264, and ZNF543) well‐distinguished CRC from adjacent normal tissues, WBCs, and 28 other types of cancer in TCGA, as well as 23 other types of cancer in GEO." (PMID 37649326, 2023).
ZNF264 also shares sentences with these, for which no sentence is quoted: bladder (1 paper); Dupuytren disease (1); endometriosis (1); Peyronie disease (1).